AQP4 (aquaporin 4)
Diseases named in the same sentence as AQP4 in open-access papers (continued):
Sharing a sentence is not in itself a finding about the gene and the disease.
ischemia (continued). "AQP4 has been suggested to regulate glymphatic flow, which could be disrupted during ischemia, leading to increased edema." (PMID 38822994, 2025). "In addition, miR-29a-5p agomir treatment suppressed the increasing expression of GSK3β, FKBP5, and AQP4 in the peri-infarction tissue compared with the ischemia-reperfusion group (p < 0.001), as shown by Western blot analysis." (PMID 40529227, 2025). "To evaluate whether ALPS indexes reflect AQP4 polarization, we analyzed its dynamic changes post-ischemia." (PMID 40837880, 2025). "Targeting AQP4 may present a novel therapeutic avenue for mitigating ischemia‐induced neuronal damage." (PMID 39444081, 2024). "The abnormally upregulating AQP4 often correlates with BBB permeability after ischemia." (PMID 37051111, 2023). "The findings presented herein support the hypothesis that such vesicles have the potential to attenuate ischemia‐mediated astrogliosis, AQP4 depolarization, impaired CSF flow, and neuroinflammation." (PMID 37554272, 2023). "Both of these studies provide a biological basis for designing AQP4 modulating agents for treating ischemia-induced CNS edema, which may also alleviate various neurological manifestations among patients with brain tumors." (PMID 35847914, 2022). "Importantly, pharmacological inhibition of AQP-4 translocation to the BSCB helps to treat ischemia- induced CNS edema and promotes functional recovery in injured rats." (PMID 35847914, 2022). "The presence of AQP4 exacerbates post-ischemic cytotoxic edema in an IS model, and several studies have demonstrated that AQP4 knockout or AQP4 gene silence attenuates ischemia-induced cellular edema, reduces mortality, restores motor function, and improves long-term outcomes." (PMID 36570843, 2022). "Also, administration of astragaloside IV and ellagic acid reduced brain edema by AQP4 inhibition after ischemia in rats." (PMID 34072678, 2021). "In particular, ischemia-induced astrocyte dysfunction can directly affect the endothelium by promoting vascular or cellular edema of aquaporin-4 (AQP4), increasing TJ and basement membrane degradation factors (MMPs), and releasing pro-inflammatory factors (IL-1β, TNF-α)." (PMID 34576209, 2021). "Aquaporin-4 (AQP4) plays an important role in the transport of water in the brain, and its depletion in astrocytes significantly reduces water permeability, resulting in the amelioration of neuronal damage and brain edema after ischemia in AQP4-knockout mice." (PMID 34072678, 2021). "However, it is understandable that AQP4 mediates the bidirectional water flux, facilitating water influx in the evolution of cytotoxic edema during early ischemia and water efflux in vasogenic edema during late ischemia or cerebral hemorrhage." (PMID 34975411, 2021). "It is well known that ischemia–reperfusion causes alteration of AQP1 and AQP4 in the retina." (PMID 32024231, 2020). "In ischemia-associated astrocytic plasticity, abnormal activity of glial fibrillary acidic protein (GFAP) and aquaporin 4 (AQP4) may play essential roles in abnormal neuronal activity or neural damages." (PMID 32985231, 2020). "AQP4 knockout mice show reduced cerebral infarction and edema following ischemia and I/R induction." (PMID 32415357, 2020). "Since the inhibition of AQP4 protein ameliorated ischemic brain injury by reducing early cytotoxic brain edema, NBP may further protect the BBB from ischemia and reperfusion injury by downregulating AQP4." (PMID 33510620, 2020). "AQP4 expression is increased in cerebral edema and ischemia." (PMID 30934923, 2019). "It has been reported that the subcellular distribution of AQP4 is sensitive to ischemia." (PMID 28317216, 2017). "Indeed, AQP4 mislocalization or knockdown has convincingly been shown to alleviate brain swelling following ischemia and other brain injuries." (PMID 28503134, 2017).
ischemia (continued). "Mitogen-activated protein kinase (MAPK) signal pathways are involved in changes in osmolality, and these pathways mediate AQP4 expression in an ischemia model, such as oxygen-glucose deprivation (OGD) in rat cortical astrocytes and middle cerebral artery occlusion (MCAO) in rats." (PMID 27517922, 2016). "AQP4 immunoreactivity was found to be increased with brain edema formation in human autopsy, and AQP4 knockout mice ameliorate brain swelling and improve outcome following ischemia, while an accelerated progression of cytotoxic brain swelling was observed in mice overexpressing glial cell AQP4." (PMID 26952102, 2016). "This indicates that AQP4 may regulate fluid distribution between brain parenchyma and blood in the formation and dissipation of cerebral edema after ischemia-reperfusion." (PMID 25904843, 2015). "Interestingly, this observation is in line with findings by a later study that shows the disruption of AQP4 square arrays in the perivascular endfeet membrane after ischemia." (PMID 26526878, 2015). "Indeed, increased extracellular levels of K+, as seen during ischemia, have been shown to increase gap junctional coupling and AQP4 expression." (PMID 25904843, 2015). "In many other animal models of experimental ischemia, AQP4 up-regulation is seen in the border zone, supporting the idea that clearance of both osmoles and water may occur at a site away from the injury core." (PMID 26526878, 2015). "The number of AQP4-positive cells increased gradually from 7.5 hours to 2 days after ischemia." (PMID 24416250, 2014). "Treadmill pre-training could significantly reduce the expression of AQP4 from 1 hour to 2 days after ischemia." (PMID 24416250, 2014). "For example, in a mouse model of ischemia using AQP4 null mice, intracranial pressure elevation, blood–brain barrier disruption, inflammation, brain edema, and neuronal apoptosis were shown to be reduced in comparison to AQP4 positive mice." (PMID 24904440, 2014). "Indeed, the absence of AQP4 was shown to prevent the formation of edema in a permanent ischemia model in AQP4-KO mice." (PMID 22778741, 2012). "The increase of AQP4-m1 early after ischemia could favor a shift toward M1 in the M1/M23 balance, which is known to favor small size OAPs." (PMID 22778741, 2012). "However, contrasting data are found in studies of other CNS disease models (such as ischemia, meningitis and trauma), in which AQP4-null mice display a better outcome, in terms of neurological score and brain water content, than wild type controls." (PMID 21054845, 2010). "In this review, we will examine AQP4’s normal role in brain water homeostasis, then review evidence from experimental models and human studies discussing AQP4’s biphasic roles: exacerbating cytotoxic edema in acute ischemia but aiding clearance of vasogenic edema once BBB disruption occurs." (PMID 40943104, 2025). "Therefore, it is possible that the reduction of AQP4 in the ventral ION in COVID-19 might be a protective response against ischemia." (PMID 37483351, 2023). "This relationship between caveolin-1 and AQP4, shown in the context of ischemia, indicates that there might be mechanisms that modify the water permeability of the perivascular barrier, based on the AQP4 intracellular relocation, in response to certain stimuli." (PMID 35454119, 2022). "And there were already a few studies that reported a negative correlation between ADCst and AQP4 during brain injury or ischemia, which were hypothesized to be associated with decreases in the extracellular space caused by cell swelling." (PMID 34712604, 2021). "After SAH, the extravasated blood constituents produced ischemia and sterile inflammation that could activate the astrocytes surrounding the arteries and increase the expression level of the Aqp4 protein, which was slightly expressed on the venous site." (PMID 33574749, 2020).
ischemia (continued). "This theory is supported by studies using models of brain edema and ischemia where electron microscopy findings demonstrate endfeet swelling of astrocytes suggesting AQP4-dependent mediated osmotic water uptake and early induction of AQP4 reduced the development of edema formation." (PMID 26941623, 2016). "Furthermore, agrin-deficient mice lack polarized localization of both β-DG and aquaporin-4 at astrocytic end-feet and do not develop cytotoxic edema after ischemia." (PMID 27690011, 2016). "Therefore, pre-conditioning training might act as an effective intervention to reduce the degree of ischemia-induced edema by lowering AQP4 expression." (PMID 24416250, 2014). "AQP0, AQP1, AQP4, and AQP9 proteins have all been found in mammalian retina, but it is the AQP4 channel that has been localized to the Müller cell endfeet in rats and chicks and has been linked to the redistribution and absorption of ischemia-induced edema in the retina and brain." (PMID 20806048, 2010). "Under ischemia or traumatic brain injury, HIF-1α escape from degradation leads to upregulation of AQP4 gene transcription as one of its target responses." (PMID 40943104, 2025). "In our study, we investigated the effect of the deletion of AQP4 and TRPV4 channels on astrocytic volume changes induced by three models of ischemia-mimicking insults." (PMID 38818517, 2024). "This is the first study that describes the impact of AQP4/TRPV4 deletion on the size of the ischemic lesion (MRI) and ECS diffusion parameters in experimental models of ischemia, OGD, hyperkalemia, and hypotonic stress in AQP4–/–/TRPV4–/– mice." (PMID 36568889, 2022). "In this study, we demonstrate that both AQP4 and TRPV4 channels, particularly their interaction, play an important role in edema formation after ischemia in vivo and under ischemia-like conditions such as OGD in situ." (PMID 36568889, 2022). "In HL-1 mouse cardiomyocyte cells, the expression of AQP-4 was increased under ischemia conditions and TGN-20, an AQP-4 inhibitor, decreased the mRNA and protein expression of AQP-4." (PMID 34942981, 2021). "On the other hand, a correlation between AQP4 expression and ADC changes was observed in meningiomas, rat models of ischemia, hydrocephalus, and AQP4-knockdown brain." (PMID 34722268, 2021). "We found that ischemia downregulated AQP4, while treatment with 2-BFI and rt-PA up-regulated AQP4 in the ischemic penumbra area." (PMID 32595494, 2020). "For instance, HIF-1α regulation of aquaporin-4 (AQP-4) and matrix metalloproteinase-9 (MMP-9) lead to edema and blood brain barrier (BBB) disruption during ischemia." (PMID 29045486, 2017). "AQP4 water receptors up-regulation was demonstrated in traumatic brain injury (TBI), ischemia, epilepsy, multiple sclerosis, HIV encephalitis, and progressive multifocal leukoencephalopathy (PML)." (PMID 24904440, 2014). "In preclinical models of ischemia and TBI, SFN significantly reduced blood–brain barrier disruption and brain edema, restored AQP4 levels, decreased infarct size and neurological deficit, and, when administered within the first hours after TBI, markedly improved spatial and working memory." (PMID 41465271, 2025). "We used three models of ischemia-related pathological conditions: hypoosmotic stress, hyperkalemia, and oxygenglucose deprivation (OGD), and observed their effect on astrocyte volume changes in acute brain slices of Aqp4–/–, Trpv4–/– and double knockouts." (PMID 38818517, 2024). "In our previous study, we demonstrated that the lack of either AQP4 or TRPV4 slows down the development of cytotoxic edema in terminal ischemia and TRPV4 deletion attenuates the ECS volume decrease induced by OGD treatment in situ." (PMID 36568889, 2022). "Contradictory to the findings that detected slower changes of brain diffusivity in AQP4–/– during acute ischemia in vivo, we did not observe a similar influence of AQP4 deletion during OGD in situ." (PMID 36568889, 2022).
ischemia (continued). "The results obtained in this study indicate that the interplay between AQP4 and TRPV4 channels may play a crucial role in the size of early edema development following ischemia." (PMID 36568889, 2022). "CAY10444 rescued the decreased expression of the tight junction (TJ) proteins zonula occludens 1 (ZO1) and occludin after ischemia induced by transient MCAO (tMCAO) and reduced the increase in aquaporin 4 (AQP4) levels after tMCAO, preserving the integrity of the BBB." (PMID 35685645, 2022). "Other research has demonstrated that AQP4 could worsen outcomes of cytotoxic edema in some models, such as TBI and ischemia." (PMID 31258460, 2019). "AQP4 controls BBB functioning, and modifying its expression or distribution may lead a consequent damage of BBB during the period of ischemia/reperfusion injury, but the exact relationship between AQP4 and BBB opening is unknown." (PMID 29682525, 2018). "They found that an increase in the colocalization of AQP4 and GLT-1 is a reaction to ischemia." (PMID 27057365, 2016). "Since ischemia is accompanied by a profound increase in [K+]o, we also estimated extracellular K+ concentrations evoked by OGD, with the expectation that they may differ in the Ctrl and AQP4–/–/TRPV4–/– mice." (PMID 36568889, 2022). "In the cardiovascular system AQP1, AQP4, AQP7, and AQP9 are expressed in endothelial cells, vascular smooth muscle cells, and cardiac tissue which all play a vital role in the development and progression of pathologies such congestive heart failure, ischemia, hypertension, and angiogenesis." (PMID 30555637, 2018). "However, there is only a slight downregulation of AQP4 expression in the postischemic rat retina, which does not support the idea that retinal edema after ischemia is due to changes in AQP4 expression." (PMID 17356517, 2007). "Thus, we showed that in AQP4 or TRPV4 knockouts, not only the specific function of these channels is affected, but also the expression of other proteins, which may modulate the ischemic cascade and thus influence the final impact of ischemia." (PMID 38818517, 2024). "The selective antagonists or blockers of AQP4 water pores has not been proven; however, the AQP4 inhibitor TGN-020 or AER-270 has beneficial effects on ischemia-induced brain edema." (PMID 36769234, 2023).
glioma (99 papers, 2011 to 2025). A benign or malignant brain and spinal cord tumor that arises from glial cells (astrocytes, oligodendrocytes, ependymal cells). "High AQP4 expression in glioma tissues has been associated with a higher prevalence of M2-like TAMs, linking AQP4 to an immunosuppressive tumor niche." (PMID 41324079, 2025). "AQP4 has been implicated in maintaining therapy-resistant niches, particularly in regions of hypoxia and low perfusion where slow-cycling, stem-like glioma cells persist." (PMID 41324079, 2025). "We also examined the expression of AQP-4 and S100B, which are frequently associated with glioma malignancy." (PMID 41154863, 2025). "We report here that the changes in the expression levels of PLEC and AQP4 correlate with each other in human astrocytoma and glioma, and that plectin-AQP4 colocalization is linked to the proliferative index (PI) of GBMs." (PMID 38263015, 2024). "In particular, M23 AQP4-OAPs triggered cell shape changes associated with alterations in the cytoskeleton of F-actin, leading to glioma cell apoptosis." (PMID 39200356, 2024). "In this study, we aimed to characterize the expression patterns of genes encoding AQP1 and AQP4 proteins and to identify the genes present in the cancerous microenvironment that potentially regulate or correlate with their expression in human gliomas." (PMID 38476871, 2024). "On the contrary, AQP4-OAPs caused a statistically significant upregulation of the KCNMA1 in U87 glioma cells in line with the elevated outward currents recorded in these cells." (PMID 39200356, 2024). "Our findings discovered for the first time that AQP4 can alter the polarization tendency of tumor-associated macrophages (TAMs), associated with the immune microenvironment of glioma, consequently causing alterations in glioma cellular states." (PMID 36599974, 2023). "The majority of the studies showed that AQP4 deficiency was associated with reduced migration capacity for example in astroglial cells or glioma cells and that high AQP4 expression was associated with tumor progression." (PMID 34099798, 2021). "The results suggested a novel miR-216a/AQP4 axis underlying LINC00461 in regulating glioma cell progression." (PMID 33817241, 2020). "In glioma, differential expression of AQP4 was pointed out in human glioma tissues, and AQP4 was upregulated in glioma-associated edema." (PMID 33817241, 2020). "The expression of IDO1/TDO was positively correlated with the expression of AQP4, which was associated with migration and invasion in glioma." (PMID 32296044, 2020). "AQP4 has been implicated to be upregulated in glioma specimens and plays a critical role in glioma-associated edema." (PMID 28264681, 2017). "Although chronic AQP4 inhibition in NMOSD may hypothetically decrease the risk of glioma development, there is currently insufficient evidence to substantiate this hypothesis." (PMID 41324079, 2025). "AQP4 expression has been found to be associated with glioma malignancies." (PMID 39247976, 2024). "Evidence has demonstrated that AQP4, which is usually highly expressed in brain tissues, promotes the tendency of tumor-associated macrophages to become M1 macrophages, thereby causing alterations in the cellular state of gliomas." (PMID 38383423, 2024). "Furthermore, aquaporin 4 expression has been linked not only to edema formation in gliomas, but also to malignancy and VEGF expression." (PMID 37893105, 2023). "The Kaplan–Meier survival analysis was performed to investigate the association between AQP4 expression and prognosis of gliomas to describe the Overall Survival (OS) curves of AQP4 over- and lower-expression groups in all gliomas (TCGA GBM and LGG), GBM, and LGG datasets, respectively." (PMID 36599974, 2023). "Aquaporin 4 overexpression has been observed in gliomas and is associated with edema formation." (PMID 37893105, 2023). "Next, we focused on the association between AQP4 and the progression of gliomas." (PMID 36599974, 2023).